INS (insulin)
Diseases named in the same sentence as INS in open-access papers (continued):
Sharing a sentence is not in itself a finding about the gene and the disease.
diabetes (continued). "The role of the virus in insulin resistance in HCV-associated diabetes is unclear, but it is thought to be secondary to either viral induced inflammation or direct interference of the virus on muscle insulin signaling." (PMID 22919404, 2012). "Diabetes of long duration treated with insulin was associated with a larger percentage of shoulder calcification." (PMID 23049626, 2012). "A recent study in women with GDM showed a decrease in insulin needs when a low GI diet was prescribed compared to the American Diabetes Association diet." (PMID 23251152, 2012). "Impaired glucose-stimulated insulin secretion in diabetes is well recognized, but its underlying mechanisms remain largely unclear." (PMID 22509386, 2012). "The underlying pathophysiology of diabetes in chronic pancreatitis is mainly based on the loss of insulin secretion." (PMID 22133269, 2011). "The role of exogenous insulin administration for cancer risk in diabetes remains controversial; further clinical trials are needed." (PMID 21773024, 2011). "A beta-cell-specific Gsα deficiency in mice results in diabetes characterized by reduced insulin secretion and beta-cell mass with the primary defect being in decreased beta-cell proliferative capacity." (PMID 21716694, 2011). "As expected, there were differences in risk factors between metformin, sulphonylureas and insulin (metformin was more often the first diabetes treatment while insulin users had more frequent history of use of other diabetes treatments)." (PMID 22164237, 2011). "Taken together, the findings of our study provide new insight into the roles of both α1-ARs and MOR in glucose homeostasis in insulin-deficient diabetes." (PMID 19095661, 2011). "The results collectively demonstrate that BBR lowers considerably the blood cholesterol and triacylglycerols while moderately improving insulin sensitivity in association with multiple risk factors of insulin resistance and diabetes." (PMID 22363882, 2011). "Type 2 diabetes results from a progressive insulin secretory defect on the background of insulin resistance." (PMID 21592922, 2011). "The observed differences, with less metabolic regulation, reflect the gradual disease progression towards diabetes, associated with increased insulin resistance for prediabetics and interconnected changes in lipoprotein metabolism." (PMID 21980352, 2011). "With regard to STZ treatment, it is well known that a single high dose induces a more rapid loss of insulin secretion and therefore more rapid onset of diabetes in mice." (PMID 22144989, 2011). "About 16.5% reported insomnia and displayed distinct metabolic changes reflecting an increase in insulin secretion, a higher risk of diabetes, and disrupted calcium signaling." (PMID 21494683, 2011). "CVA was associated with short duration of diabetes in the FF and FP groups, and insulin use was associated in the FP group." (PMID 21978180, 2011). "In that vein, chronic inflammation, increased free fatty acids, and elevated oxidative stress associated with diabetes inhibit insulin signaling by increasing serine phosphorylation of IRS1 in muscle and adipose tissue." (PMID 21754917, 2011). "Type 1 Diabetes Mellitus is caused by auto immune destruction of insulin producing beta cells in the pancreas." (PMID 21687731, 2011). "Fourteen loci (61%) are associated with both diabetes (glucose levels, glucose tolerance, and serum insulin) and obesity (fatpad and organ weights)." (PMID 21931559, 2011). "In the present review, we used our recent data to describe the advance in plasma glucose-lowering action of herbal products, especially the mediation of β-endorphin in glucose homeostasis of insulin-deficient diabetes." (PMID 19095661, 2011). "PIK3R1 (ranked at 1) had been tested for their influence on insulin action, showing significant associations with diabetes." (PMID 21799737, 2011). "It was known that the insulin resistance in skeletal muscle is a major pathogenic factor in diabetes mellitus." (PMID 21935427, 2011).
diabetes (continued). "Diabetes mellitus is a disease due to abnormality of carbohydrate metabolism and it is mainly linked to low blood insulin level or insensitivity of target organs to insulin." (PMID 23493848, 2011). "Diabetes mellitus is a metabolic disorder characterized by loss of insulin production or efficacy and glycemic dysregulation." (PMID 21633715, 2011). "First, a widely used rodent model of diabetes—the Goto-Kakizaki (GK) rat —was shown to harbor missense mutations in the IDE gene that decrease the efficiency of insulin degradation." (PMID 21695259, 2011). "Diabetes results from abnormal metabolism of insulin wherein insulin action is impaired, or absolute insulin deficiency results in imbalance of glucose metabolism and leads to a syndrome called diabetes mellitus." (PMID 19389871, 2011). "Two new transgenic mouse models have been produced that demonstrate how AD pathology can exacerbate insulin signaling deficiencies and glucose tolerance and how diabetes can enhance cerebrovascular Aβ deposition and amyloid mediated vascular inflammation." (PMID 22654727, 2011). "The number of individuals diagnosed with type 2 diabetes mellitus, which is caused by insulin resistance and/or abnormal insulin secretion, is increasing worldwide, creating a strong demand for the development of more effective anti-diabetic drugs." (PMID 21479175, 2011). "Insulin-degrading enzyme (IDE) is a thiol sensitive peptidase that degrades insulin and amyloid β, and has been linked to type 2 diabetes mellitus and Alzheimer's disease." (PMID 21448434, 2011). "The finding that higher counts of concomitant diabetes medications were positively associated with insulin persistence is inconsistent with existing literature." (PMID 21226935, 2011). "Crossing APP23 transgenic mice with ob/ob (leptin deficient) mice resulted in enhanced diabetes symptoms (blood glucose levels and plasma insulin) compared to ob/ob mice alone, but with reduced insulin levels in the brain." (PMID 22654727, 2011). "Insulin-deficient diabetes increases retinal cell death within 4 weeks after diabetes onset in rats and increased neuronal apoptosis has been documented in post-mortem human eyes." (PMID 22046295, 2011). "The reduced brain insulin signaling associates with increased Aβ levels in mouse model of diabetes, and hyperinsulinemia increases risk of AD in man." (PMID 21568932, 2011). "Mutations in the insulin gene cause diabetes in humans and in the Akita mouse where insulin misfolding leads to ER stress and apoptosis and clinically manifests as irreversible β-cell failure." (PMID 21423765, 2011). "Among these genes, ATF6 is a strong candidate by its biological function in endoplasmic reticulum stress and unfolded protein response, which linked insulin demand with beta cell failure and diabetes." (PMID 21211013, 2011). "Insulin resistance has been observed in other mouse models with insulin deficient diabetes and results from chronically elevated blood glucose levels, and reduced fat and muscular tissue." (PMID 21818396, 2011). "Insulin resistance, however, can develop up to a decade before the onset of diabetes, and insulin insensitivity increases the risk of macroangiopathy." (PMID 21754922, 2011). "When the polymorphisms were included in a multiple linear regression model adjusting for diabetes status, sex, and age, the A5227G polymorphism was associated with diastolic BP (P = .008) and serum levels of insulin (P = .039) in all subjects." (PMID 20619427, 2011). "On the other hand, the associations between the FAPB2 polymorphism and diabetes remain inconsistent despite the fact that the polymorphism has been associated with postprandial glucose and insulin levels." (PMID 21941641, 2011). "The β-cell dysfunction has been attributed in part to loss of β-cell mass via apoptosis with inadequate insulin secretion leading to hyperglycemia and other diabetes symptoms." (PMID 21541314, 2011).
diabetes (continued). "Insulin resistance precedes diabetes onset in KK-Ay mice and typically causes higher plasma insulin levels." (PMID 21774832, 2011). "Disturbances in leptin and insulin signaling pathways are related to obesity and metabolic syndrome (MS) with increased risk of diabetes and cardiovascular disease." (PMID 22185674, 2011). "Overall, our findings demonstrated that the control of precursor maturation and disposal acts as an early regulative mechanism in normal insulin production, and its disorder is crucially linked to β-cell failure and diabetes pathogenesis." (PMID 21559376, 2011). "In diabetes, protein catabolism is increased due to deficiency of carbohydrate-derived energy in connection with low-serum insulin." (PMID 20981322, 2011). "A prospective population-based study with 6,370 elderly subjects found that the risk for both overall dementia and Alzheimer's disease was increased by diabetes, with an even higher risk among people treated with insulin (of presumably more severe disease)." (PMID 22389813, 2011). "Type 1 diabetes mellitus (T1DM) is characterized by an absolute deficiency of insulin secretion with hyperglycemia as a consequence." (PMID 22013504, 2011). "When patients with clinical diabetes were stratified by antidiabetic therapy, only those on insulin treatment showed significantly increased all-cause mortality, with an adjusted risk ratio of 2.11 (95% CI: 1.48-3.00)." (PMID 21569580, 2011). "Herein, we describe recent advances in insulin-independent mechanism(s) of herbal products in the management of glucose metabolism in insulin-deficient diabetes." (PMID 19095661, 2011). "Evidence show that some medications for diabetes such as metformin can decrease the risk of cancer, whereas use of exogenous insulin and insulin secretagogues such as sulfonylureas can increase the risk of cancer incidence and/or mortality." (PMID 22205924, 2011). "Reduction in insulin-mediated glucose uptake caused by lower gene expression of GLUT 4 in diabetes has been observed." (PMID 19095661, 2011). "These three cases further confirm the essential features of diabetes caused by INS mutations with proteotoxic effect." (PMID 23074673, 2011). "Insulin resistance is at the core of obesity associated diabetes and is thought to reflect impaired insulin signaling due to chronically increased levels of free fatty acids (FFA)." (PMID 21541314, 2011). "Diabetes mellitus (DM) is a chronic disease caused by inherited and/or acquired deficiency in production of insulin by the pancreas, or by the ineffectiveness of the insulin produced." (PMID 22134398, 2011). "AR deficiency plays key roles in the development of insulin and leptin resistance, which explains increased diabetes incidence in elder male." (PMID 21689475, 2011). "The present study was carried out to determine the effect of berberine on glucose homeostasis and several biomarkers associated with insulin sensitivity in male Wistar rats with intraperitoneal injection of streptozotocin (STZ)-induced diabetes." (PMID 22363882, 2011). "In the DPP, the diabetes risk T allele at rs7903146 was also associated with impaired insulin secretion." (PMID 21814547, 2011). "Many have taken the position that there is a positive association between diabetes or insulin signaling deficits and AD based on epidemiological data as well as animal or cellular models." (PMID 22654727, 2011). "The gene-encoding SorCS1, SORCS1 (chromosome 10), has been associated with insulin signaling and diabetes mellitus." (PMID 22191060, 2011). "In humans, disturbance in insulin sensitivity leads to impaired clearance of glucose from the blood stream, which is a hallmark of diabetes." (PMID 22242005, 2011). "Streptozotocin (STZ) destroys the insulin producing β-cells in the pancreas, causing a diabetes-like status (hyperglycemia) to the experimental animals." (PMID 22145108, 2011).
diabetes (continued). "This weight loss improves insulin sensitivity and reduces the frequency and severity of metabolic syndrome, diabetes and its complications." (PMID 21918648, 2011). "In Cox models, adjusting for diabetes duration, body mass index and sex, insulin therapy was related to higher cancer risk (HR = 1.25 [1.17 - 1.33])." (PMID 21752291, 2011). "More positive experiences with insulin therapy were significantly associated with shorter duration of diabetes, less symptom distress, and greater well-being, self-efficacy and treatment satisfaction." (PMID 20370840, 2010). "Obesity, mainly of the abdominal type, is associated with resistance to the effects of insulin on peripheral glucose and fatty acid utilization, often leading to type 2 diabetes mellitus." (PMID 20507559, 2010). "Contributing factors to the neuropathy phenotype in rodents include background strain, diet composition, insulin/C-peptide deficiency, coexisting hyperglycemia and hypertension and duration of diabetes." (PMID 20871761, 2010). "In the present study, a mouse model of combined insulin-deficient diabetes and AD was made by injecting APP/PS1 transgenic mice with STZ, a known toxin for pancreatic insulin-producing β-cells." (PMID 21044348, 2010). "Obesity is an important cofactor in type 2 diabetes because the presence of obesity and diabetes together is associated with more severe insulin and leptin resistance than either condition alone." (PMID 20181219, 2010). "The IITQ covers a broader range of outcomes than other instruments designed to assess general diabetes treatment satisfaction (DTSQ) or PRO associated with inhaled insulin therapy." (PMID 20334647, 2010). "Impairment of glucose transport in splenocytes and thymocytes and its regulation by insulin is a common feature of human diabetes, enhancing susceptibility to infections." (PMID 21044347, 2010). "Diabetes mellitus is a common metabolic disease which is a result of either a deficiency in insulin secretion, or insulin resistance in body cells." (PMID 22577407, 2010). "Insulin is a major therapeutic tool for insulin-deficient patients with type 1 diabetes mellitus, and also for patients with type 2 diabetes mellitus (T2D), with both insulin resistance and a relative insulin deficiency." (PMID 20721344, 2010). "Understanding the biochemical networks underlying metabolic homeostasis and their association with insulin sensitivity will help to clarify diabetes etiology, and should foster the discovery of new biomarkers of disease risk and severity." (PMID 21170321, 2010). "It is induced in the liver during fasting and is elevated in several models of diabetes or deficiency in insulin signalling." (PMID 20700401, 2010). "Insulin gene (INS) mutations have recently been described as a common cause of permanent neonatal diabetes (PNDM) and a rare cause of diabetes diagnosed in childhood or adulthood." (PMID 20226046, 2010). "Cognitive impairments associated with diabetes caused by inadequate insulin/insulin receptor functions have also been documented." (PMID 20868513, 2010). "Iron overload form hereditary hemochromatosis is associated with diabetes and impaired glucose tolerance and decreased insulin secretory capacity, which is reportedly reversed with phlebotomy therapy." (PMID 20854668, 2010). "On the other hand, the pathogenesis of diabetes mellitus is reportedly associated with PA related to impaired insulin secretion due to hypokalemia." (PMID 21171971, 2010). "Inhibition of IKKβ activity prevents diet-induced diabetes in P. obesus and inhibits IL-1β induced reactive oxygen species, loss of insulin production and beta cell death in vitro." (PMID 20948968, 2010). "Of interest, some prospective data showed that diabetes mellitus is a statistically risk factor of osteoporosis especially in insulin treated diabetes, long history of diabetes or in elderly." (PMID 20205769, 2010).
diabetes (continued). "A study exploring the relationship between marital relational domains such as intimacy and adjustment in insulin-treated adults with type 1 and type 2 diabetes concluded that the quality of marriage was associated with adaptation to diabetes." (PMID 20825634, 2010). "Loss of insulin production is expected to coincide with the loss of insulin production and beta cell destruction reported during the late stage of diabetes development in this animal model." (PMID 20948968, 2010). "Consistent with previous reports, our findings showed that insulin deficient diabetes induced by STZ exacerbated the accumulation of Aβ in APP/PS1 transgenic mice." (PMID 21044348, 2010). "Among the second-generation antipsychotics, clozapine and olanzapine are associated with the highest risk of weight gain, as well as changes in insulin sensitivity and lipid metabolism, which increase the risk of diabetes and cardiovascular disease." (PMID 20631894, 2010). "The relative or absolute insulin deficiency observed in diabetes is in many cases due to a defective insulin biosynthesis insufficient to meet the demand for extended periods of insulin hypersecretion." (PMID 20520763, 2010). "Insulin sensitizers like Rosiglitazone and metformin are being evaluated for primary prevention of type 2 diabetes mellitus in high-risk patients." (PMID 20814523, 2010). "The present data indicate that dysfunction of the insulin signaling pathway during insulin deficient diabetes contributes to the enhanced progression of AD." (PMID 21044348, 2010). "Diabetes is a metabolic disorder which is characterized by hyperglycemia and glucose intolerance due to insulin deficiency, impaired effectiveness of insulin action or, both." (PMID 20634940, 2010). "As a consequence, several functional polymorphisms from the insulin – IGF2 region have been frequently implicated with diabetes and/or obesity in association or linkage based studies." (PMID 21637566, 2010). "Pulsatile arterial compression of the right anterolateral medulla oblongata is associated with autonomic dysfunction, including “driving” the pancreas, which increases insulin resistance causing type 2 diabetes mellitus." (PMID 20847912, 2010). "Insulin is a vital peptide hormone that is a central regulator of glucose homeostasis, and impairments in insulin signaling cause diabetes mellitus." (PMID 20498699, 2010). "These include transcription factors concerned with the control of: adipogenesis (Pparγ, Klf15, Irf1, Creb1, Egr2, Gata3); lipogenesis (Mlxipl, Srebp1c); inflammation (Jun, Stat3); insulin signalling and diabetes susceptibility (Foxo1, Tcf7l2)." (PMID 21187013, 2010). "Currently, one of the most studied phenomena is how obesity-related inflammation affects insulin sensitivity and causes morbidities such as diabetes, cardiovascular disease and cancer." (PMID 20307313, 2010). "Genetic deficiency of insulin expression can cause diabetes, but MIDY patients are heterozygotes and INS-gene haploinsufficiency is not itself a sufficient basis for diabetes, at least not in mice." (PMID 20948967, 2010). "STZ selectively destroys pancreatic β cells and destruction of β cells is associated with deficiency of insulin and induction of insulin-dependent diabetes mellitus (IDDM)." (PMID 21713142, 2010). "Diabetes mellitus (DM), a leading metabolic disorder worldwide, is characterized by hyperglycemia associated with impairment in insulin secretion and/or insulin action as well as alteration in intermediary metabolism of carbohydrates, proteins and lipids." (PMID 20431798, 2010). "Insulin-naïve patients demonstrated a significantly shorter disease duration and had significantly fewer diabetes-associated complications." (PMID 20920319, 2010). "Patients with diabetes on insulin replacement were at a greater risk for the development of foot ulcers as compared to those on diet and oral anti-diabetic medication." (PMID 20606950, 2010).